PER2 (period circadian regulator 2)
Diseases named in the same sentence as PER2 in open-access papers (continued):
Sharing a sentence is not in itself a finding about the gene and the disease.
tumor (continued). "Yet we find that T cell depletion does not compensate for the Per1–/–Per2–/–-driven inhibition of tumor growth, nor do we detect immune cell transcriptional signatures in early stages of metastases formation, suggesting that the adaptive immune microenvironment does not mediate this effect." (PMID 33123539, 2020). "Besides the well-known tumour suppressive role of miR-34a, we also reported a negative correlation between the expression of the clock gene PER2 and miR-34a." (PMID 31658284, 2019). "Interestingly, tumor volumes were indistinguishable at 24 hours but expression levels of Per2 were different in each irradiated group." (PMID 27036047, 2016). "The role of PER2 as a tumor suppressor may not be applicable in all cancers." (PMID 24708606, 2014). "Additionally, for the genes PRKAB1, PRKAB2, PER1, PER2, and PER3, methylation was observed in all samples, regardless of the tumor grade." (PMID 39001398, 2024). "Moreover, the absence of PER2 expression has been shown to elevate the levels of TNF-α and IL-6, thus augmenting tumor-related inflammation." (PMID 38607733, 2024).
cancer (139 papers, 2009 to 2025). A tumor composed of atypical neoplastic, often pleomorphic cells that invade other tissues. "Consistently, downregulation of the clock gene PER2 has been linked to the development of a variety of cancers." (PMID 40521302, 2025). "While circadian rhythms orchestrate various physiological processes, circadian genes such as Per1 and Per2 have been implicated in cell cycle regulation, DNA damage response, and apoptosis, which are critical in cancer development and progression." (PMID 39012661, 2024). "At present study, we observed multiple circadian genes, particularly PER2 and PER3, were downregulated in cancer tissue, likewise, Xiong also found that loss of PER2 expression was closely associated with the genesis and development of HNSCC37." (PMID 37968308, 2023). "PER2 is also deregulated in cancer, its expression is lower in breast cancer tissue and the knockout of mPer2 gene increases cancer risk as it regulates DNA damage-responsive pathways." (PMID 36731029, 2023). "Studies conducted with animal models and epidemiological analyses further demonstrate that loss of PER2 function contributes to dysregulated mitochondrial metabolism in cancer initiation potential." (PMID 36465103, 2022). "We further show that loss of Per2 in the TME leads to significant transcriptional changes in response to cancer cell introduction." (PMID 33123539, 2020). "A total of 6 studies reported the association between the expression of PER2 mRNA and cancer prognosis." (PMID 32849922, 2020). "Mutations or deletions in the Per2 gene during tumorigenesis, and Per2 overexpression can regulate expression of the genes associated with the cell cycle and apoptosis, which have a role in cancer suppression and cisplatin treatment." (PMID 33083827, 2020). "In summary, the loss of function of Per2 critically deregulated the circadian clock and clock-controlled pathways, whose alteration contributed to three cancer hallmarks, within the initial 3 weeks of DEN exposure." (PMID 27494874, 2016). "The variants for Cry1 rs1056560 are correlated to cancer, which elevate the risk in about 11% (OR 1.11); Per2 rs934945 in about 15% (OR 1.15); and Clock rs3805151 in about 35% (OR 1.35)." (PMID 27313610, 2016). "Mice lacking the circadian genes Period1 and 2 (Per) or Cryptochrome1 and 2 (Cry) are deficient in cell cycle regulation and Per2 mutant mice are cancer-prone." (PMID 20539819, 2010). "In addition, mice with Per2 mutations are susceptible to cancer, whereas ectopic expression of Per1 and Per2 can lead to growth inhibition." (PMID 38903177, 2024). "Conversely, Per2 mutations are associated with an increased risk of certain cancers, suggesting a complex role in tumorigenesis that might be context-dependent." (PMID 39012661, 2024). "However, some studies demonstrated that clock gene mutations (including Clock, Per1−/− or Per2−/−, Cry1−/− and Cry2−/−) potentially led to an adverse influence on cancer progression." (PMID 35246220, 2022). "The association of Per2 or Pai-1 in many types of cancer, including breast, is well-documented." (PMID 33633796, 2021). "Loss of PER2, a core circadian component, is linked to cancer predisposing." (PMID 28108951, 2017). "Furthermore, the down regulation of Per2 expression in human cancers was usually associated with poor patient outcomes." (PMID 27494874, 2016).
cancer (continued). "The suppressed PER2 expression drives enhanced glycolytic flux, effectively promoting the Warburg effect characteristic of cancer metabolism." (PMID 41184251, 2025). "The inhibition of CK1δ using PF-670462 has shown potential in reducing PER1, PER2, and other clock genes in rats and is suggested as a cancer therapeutic agent." (PMID 40002179, 2025). "Period2 (PER2) is a core biological clock gene, and downregulation of its expression promotes the development of a variety of cancers, including OSCC, lung cancer, and breast cancer." (PMID 40113747, 2025). "Taken together, the Per2 gene optimizes the balance between cell death and cell survival and affects the cellular response to oxidative stress in a manner that influences cancer development and the aging process." (PMID 38524161, 2024). "In recent years, studies have shown that the aberrant expression of PER2 is responsible for not only circadian rhythm alterations but also the occurrence and development of cancers." (PMID 38334624, 2024). "In cases of cancer, it has been observed that the expression of various core circadian genes such as PER2 is downregulated." (PMID 38334624, 2024). "Overexpression of Per2 in the carcinoma cell line leads to a downregulation of the Bcl2 gene and increased apoptosis." (PMID 38524161, 2024). "The dysregulation of circadian genes in cancer leads to the downregulation of PER2 and the upregulation of β-catenin protein levels, which can cause the proliferation of CRC cells." (PMID 38023143, 2023). "With respect to the possible use of miR-34a in cancer treatment, per2 can be considered as an off-target gene." (PMID 37831728, 2023). "This molecule can inhibit multiple phosphorylation sites on clock proteins, including PER2 S693, leading to decreased cancer cell growth." (PMID 36672355, 2023). "A differential MACC1 expression in HCT116 cells upon C. cardunculus treatment, as seen in WT and PER2-KO conditions, points towards the effect of C. cardunculus on clock and metastasis-related components with likely effects on cancer progression." (PMID 36012399, 2022). "In line with this, the disruption of the core clock Per2 gene further aggravated CRC cancer cell proliferation in ApcMin/+ genetic mice." (PMID 35246220, 2022). "Overexpression of per2 sensitised cancer cell lines Panc1 and Aspc1 to cisplatin, inhibited cell proliferation and induced apoptosis." (PMID 36361993, 2022). "By using a bioluminescent reporter under the control of the PER2 promoter in esophageal cells, we have observed the oscillation of PER2 expression in human cancer cells in vitro in spite of the deregulated circadian clock gene expression." (PMID 33810377, 2021). "In spite of the downregulation of clock related genes in cancer, the persistence of a circadian clock or at least of PER2 oscillations have been reported in several cancer models." (PMID 33810377, 2021). "In the present study, we confirm that PER2 oscillations still occur in human cancer cells in vitro in spite of a deregulated circadian clock gene expression." (PMID 33810377, 2021).
cancer (continued). "PER2 has a critical role in controlling the malignancy of cancers and also showed a mechanism regulating the resistance of oncogene-transformed PER2m/m cells against the cytotoxicity of chemotherapeutic drugs." (PMID 33042011, 2020). "Low expressions of Per1 and Per2 were related to poor OS in patients with cancers (Per1: HR=1.35, 95%CI: 1.06∼1.72, P=0.014 and Per2: HR =1.43, 95%CI: 1.10∼1.85, P=0.007), with high observed heterogeneity (Per1: Ι2=77.1%, P<0.001 and Per2: Ι2=63.1%, P=0.006)." (PMID 32437452, 2020). "The research results demonstrated that the protein expression levels of PER1, PER2, and PER3 were significantly associated with the survival and prognosis of patients with cancer." (PMID 32849922, 2020). "Accordingly, the highest nucleic PER2 levels were in NT compared with the lowest in OSCC, suggesting the loss of PER2 nucleus-translocation function in cancer as well as in ANT." (PMID 32185221, 2020). "Hierarchical clustering highlighted 1222 differentially expressed genes between WT and Per2–/– livers injected with PBS or with MC38 cancer cells." (PMID 33123539, 2020). "There were 6 studies with a total of 427 cases that assessed PER2 mRNA expression in the prognosis of cancer and only 1 study with a total of 29 cases that assessed PER3 mRNA expression in the prognosis of cancer." (PMID 32849922, 2020). "Among these rhythm genes, PER1, PER2, PER3, and TIMELESS are the most frequently mutated genes in pan‐cancer." (PMID 31927791, 2020). "Principal component analysis (PCA) showed that the basal transcriptional landscape of WT and Per2–/– livers is different, and further changes following injection of cancer cells." (PMID 33123539, 2020). "Our results showed that low Per1, Per2, Per3 and Npas2 expression played a distinct and crucial role in progression of cancers." (PMID 32437452, 2020). "Per1, Per2 and Per3 were reported to play an important role in regulating cancer cell growth, proliferation and apoptosis." (PMID 32437452, 2020). "Our study suggested that low Per1, Per2 and Npas2 expression played a distinct and crucial role in progression of cancers." (PMID 32437452, 2020). "Here we found that expression of the core clock gene Per2 in the TME supports different stages of cancer progression." (PMID 33123539, 2020). "Several studies have shown that abnormal expression of the Per2 gene has an important role in the occurrence and development of cancer." (PMID 33083827, 2020). "Studies on animals have shown that PER2 knockout rodents are more prone to cancer initiation after gamma radiation in comparison to wild type mice." (PMID 31739444, 2019). "PER2 is a key regulator of the cellular clock and it appears to be particularly important in the occurrence, development and progression of cancer." (PMID 33089179, 2019). "Decreased expression through hypermethylation of CpG islands or aberrant acetylation in the promoters of the core circadian genes Per1, Per2, and Per3 are reported in a spectrum of human cancers." (PMID 31409384, 2019). "Further cancer hallmark analysis reveals that several core clock genes highly correlate with apoptosis and cell cycle such as RORA and PER2." (PMID 31881010, 2019). "Overexpressing and downregulating Per1 or Per2 inhibits and accelerates growth of cancer cells, respectively." (PMID 29607311, 2018). "Significantly decreased transcript levels of CRY1, PER2 were observed in Carcinoma ductale and mix types of carcinomas." (PMID 29958276, 2018). "The clinical relevance of our findings is illustrated by the fact that Per2 expression was also decreased in human HCC as well as in other human cancers, as compared to the corresponding healthy tissues." (PMID 27494874, 2016).
cancer (continued). "The MCF-12A breast epithelial cells show a predominant localization of Per2 within the cytoplasm, with slight colocalization in the nucleus, whereas the MDA-MB-231 cancer cells show a more prominent nuclear colocalization of Per2." (PMID 26347774, 2015). "To our knowledge we have, for the first time, demonstrated a clear circadian pattern in Per2 protein expression in the normal MCF-12A cells as well as in the ER- MDA-MB-231 cancer cells exists." (PMID 26347774, 2015). "In conclusion, our results demonstrate the influential role Per2 plays in the circadian efficacy and toxicity of the most important chemotherapeutic agent used in the treatment of cancer to date." (PMID 26347774, 2015). "Transfecting human cancer cell lines with Per1 and Per2 expression plasmids led to cessation of growth." (PMID 25760074, 2015). "To evaluate the mechanism whereby Per2 silencing increases cell death in the MDA-MB-231 cancer cells, we evaluated the cleavage of the apoptotic markers caspase-3 and poly-ADP-ribose polymerase (PARP) with the use of western blotting." (PMID 26347774, 2015). "The unexplored and highly novel avenue of the circadian clock genes, including Per2, as adjuvant cancer targets warrants further investigation." (PMID 26347774, 2015). "Overexpression of Per1 and Per2 sensitized human cancer cells to DNA damage-induced apoptosis, while inhibiting expression of these genes in similarly treated cells reduced apoptosis." (PMID 25760074, 2015). "In sum, this report provides evidence that the circadian clock gene Per2 influences cellular response to oxidative stress and modulates cell death, which in turn affects cancer development and the aging process." (PMID 25628599, 2014). "Cancer cells also express higher levels of PER2 compared to normal cells; correspondingly, PER2 circadian expression has been shown to modulate proliferative, cell cycle, and apoptotic pathways, specifically c-myc, cyclin D, β-catenin, and VEGF." (PMID 23675573, 2013). "At the molecular level, Per1 and Per2 are involved in the DNA damage response, and overexpression of either protein inhibits cancer cell growth and increases the apoptotic rate, supporting the notion that they participate in tumor suppression." (PMID 23563360, 2013). "We found that when kept in 24 hour alternating light-dark conditions (24hr LD cycles), mice deficient in Bmal1 (Bmal1+/−), Cry1 and Cry2 (Cry1−/−;Cry2−/−), Per1 and Per2 (Per1−/−;Per2m/m) or Per2 alone (Per2−/−) were all cancer-prone." (PMID 20539819, 2010). "Also consistent with Per1, the genes induced by Per2 overexpression did not include putative atrophy associated genes such as Murf1 or Mafbx or those shown to be altered by Per2 induction in cancer cells." (PMID 40632504, 2025). "The circadian clock, governed by core-clock genes such as BMAL1 and PER2, orchestrates various physiological processes, including metabolism, cell proliferation, and responses to medications, making them a crucial target for improving cancer therapy outcomes." (PMID 40382284, 2025). "Similarly, PER2 affects cancer metastasis by repressing EMT-related genes like TWIST1 and SLUG through interactions with polycomb proteins and HDAC2." (PMID 39566400, 2024). "Genes like PER2 and ARNTL2 have significant involvement in the mechanisms of the biological clock, and their variations are strongly associated with the regulation of sleep homeostasis, hormonal imbalances, cancer, and ultimately the development of CRF." (PMID 39372868, 2024). "Likewise, the clock gene PER2 in mammalians is responsible for inhibiting the formation of tumors and the proliferation of cancer cells, both in vivo and in vitro." (PMID 38892035, 2024).